GBP2 (guanylate binding protein 2)
Description:
Interferon (IFN)-inducible GTPase that plays important roles in innate immunity against a diverse range of bacterial, viral and protozoan pathogens. Hydrolyzes GTP to GMP in 2 consecutive cleavage reactions, but the major reaction product is GDP. Following infection, recruited to the pathogen-containing vacuoles or vacuole-escaped bacteria and acts as a positive regulator of inflammasome assembly by promoting the release of inflammasome ligands from bacteria (By similarity). Acts by promoting lysis of pathogen-containing vacuoles, releasing pathogens into the cytosol (By similarity). Following pathogen release in the cytosol, promotes recruitment of proteins that mediate bacterial cytolysis: this liberates ligands that are detected by inflammasomes, such as lipopolysaccharide (LPS) that activates the non-canonical CASP4/CASP11 inflammasome or double-stranded DNA (dsDNA) that activates the AIM2 inflammasome (By similarity). Confers protection to the protozoan pathogen Toxoplasma gondii (By similarity). Independently of its GTPase activity, acts as an inhibitor of various viruses infectivity, such as HIV-1, Zika and influenza A viruses, by inhibiting FURIN-mediated maturation of viral envelope proteins.
Tractability: Small molecule: a structure with a bound ligand is known. PROTAC: UniProt records ubiquitination sites on it; ubiquitination databases record sites on it; its protein half-life has been measured.
Gene: Protein-coding gene on chromosome 1 (89,106,132 to 89,150,456, reverse strand). Ensembl gene ENSG00000162645.
Subcellular location: Cytoplasmic vesicle membrane; Golgi apparatus membrane; Cytoplasm; Cytoplasm, perinuclear region
Subcellular location (Human Protein Atlas): Cytosol; Nucleoplasm
Pathways (Reactome):
Immune System: CASP4 inflammasome assembly; GBP-mediated host defense; Interferon alpha/beta signaling; Interferon gamma signaling
Disease: Enterobacterial factors antagonize host defense
Gene Ontology:
Molecular function: GTPase activity; identical protein binding; molecular function inhibitor activity; protein binding; protein homodimerization activity; GTP binding
Biological process: cellular response to interleukin-1; cellular response to tumor necrosis factor; cellular response to type II interferon; defense response to virus; protein localization to nucleus; activation of innate immune response; cellular response to lipopolysaccharide; cytolysis in another organism; defense response to bacterium; defense response to Gram-positive bacterium; defense response to protozoan; immune response; positive regulation of AIM2 inflammasome complex assembly; positive regulation of pyroptotic inflammatory response
Cellular component: cytoplasm; cytosol; Golgi apparatus; Golgi membrane; nucleus; perinuclear region of cytoplasm; cytoplasmic vesicle; cytoplasmic vesicle membrane
Genetic constraint (gnomAD): Loss-of-function variants: 46 observed, 54.67 expected, observed/expected ratio (o/e) 0.84, 90% interval 0.66 to 1.08. The upper end of that interval is the gene's LOEUF score, 1.08, which puts it in group 4 of 6, group 1 being the genes least tolerant of losing a copy. Missense variants: 597 observed, 671.08 expected, observed/expected ratio (o/e) 0.89, 90% interval 0.83 to 0.95. Synonymous variants: 227 observed, 249.71 expected, observed/expected ratio (o/e) 0.91, 90% interval 0.81 to 1.01.
Homologues: Orthologues: chimpanzee GBP2 (100% identical), pig GBP2 (74% identical), mouse Gbp2 (71% identical), rat Gbp2 (71% identical), mouse Gbp2b (70% identical), tropical clawed frog gbp1 (49% identical), zebrafish gbp2 (46% identical), Drosophila melanogaster atl (19% identical). Paralogues in human: GBP1 (76% identical), GBP3 (75% identical), GBP5 (64% identical), GBP7 (55% identical), GBP4 (54% identical), GBP6 (53% identical), ATL2 (20% identical), ATL3 (20% identical), ATL1 (20% identical), RNF112 (13% identical).
Diseases named in the same sentence as GBP2 in open-access papers:
GBP2 is named in the same sentence as 120 diseases in open-access papers, as found by Europe PMC text mining. Sharing a sentence is not in itself a finding about the gene and the disease. The quoted sentences say what the papers report.
breast carcinoma (31 papers, 2009 to 2025). "The expression level of GBP2 was higher in breast cancer, but high GBP2 expression is associated with better prognosis in breast cancer patients." (PMID 34439200, 2021). "In this research,the promoter methylation status of GBP2 gene, as well asGBP2 methylation status association with clinicopathologiccharacteristics were investigated in breast cancer." (PMID 33211060, 2020). "The results showed that promotermethylation of GBP2 in tumors of breast cancer patients wassignificantly associated with some malignant indicators including lymph nodeinvolvement, distant metastasis and, higher cancer stages." (PMID 33211060, 2020). "In summary, our data provide new insights into the function and molecular mechanisms underlying GBP2’s regulation of breast cancer cell invasion." (PMID 29072687, 2017). "GBP2 was associated with a better prognosis in breast cancer and a more efficient T cell response." (PMID 35222540, 2022). "High GBP2 expression could inhibit Drp1-mediated breast cancer invasion and reduce the risk of tumor recurrence." (PMID 29072687, 2017). "GBP2’s anti-tumor effects in breast cancer hinge on mitochondrial dynamics and autophagy, while its pro-tumor role in glioblastoma leverages fibronectin remodeling and Stat3 activation, reflecting TME-specific signaling." (PMID 40564939, 2025). "In mouse mammary carcinoma 67NR cells, GBP2 promotes cellular projections and filopodia formation, indicating cell division cycle 42 activation, while also upregulating RhoA activity." (PMID 41181145, 2025). "In breast cancer, GBP2 blocks dynamin-related protein 1 translocation from the cytosol to mitochondria, thereby attenuating dynamin-related protein 1-dependent mitochondrial fission and cancer cell invasion." (PMID 41181145, 2025). "Contrarily, GBP2 inhibits breast cancer metastasis by regulating Rho GTPases, limiting invadosome formation and cell migration—a protective cytoskeletal brake driven by its GTPase activity and autophagy induction." (PMID 40564939, 2025). "GBP2’s beneficial effects in breast cancer contrast with its role in driving malignancy in renal carcinoma, necessitating precise targeting strategies, which can be evaluated through tumor-specific expression profiling or patient stratification." (PMID 40564939, 2025). "In sarcomas, breast cancer and colorectal cancer, GBP2 shapes the immune microenvironment, and an elevated GBP2 expression is related to a favorable response to anti-PD1 therapy and to tumor-infiltrating T cells." (PMID 37370817, 2023). "GBP2 was also identified as a prognosis-related biomarker and immunotherapeutic target in several human cancers including colorectal cancer and breast cancer." (PMID 37745978, 2023). "In breast cancer, GBP2 inhibits mitochondrial fission and cell invasion, and GBP2 overexpression is correlated with a better prognosis." (PMID 35436989, 2022). "It has been documented that the upregulation of guanylate-binding protein 2 (GBP2), a GTPase, is linked to a better prognosis in breast cancer patients." (PMID 36192752, 2022). "The literature on GBP-2 suggests that it would promote a good prognosis in breast cancer by inhibiting cell migration/invasion." (PMID 35681772, 2022). "Work in breast cancer cells extended this work by showing that GBP-2 inhibits cell migration and invadosome formation, accompanied by inhibition of Rac1 and activation of Cdc42 and RhoA." (PMID 35681772, 2022). "While in breast cancer, GBP2 can also be stated as a tumor suppressor gene according to experimental evidence of scientists." (PMID 35345444, 2022). "GBP-2 inhibits breast cancer cell migration by inhibiting the activation of Rac1, while promoting the activation of CDC42 and RhoA." (PMID 35681772, 2022). "GBP-2 has also been suggested to inhibit breast cancer cell migration and invasion by inhibiting mitochondrial fission by blocking the ability of Drp1 to translocate to the mitochondria." (PMID 35681772, 2022).
breast carcinoma (continued). "Recently, three members of the Guanylate-Binding Protein (GBP) family of interferon-induced GTPases, GBP-1, GBP-2, and GBP-5, have been implicated to play roles in breast cancer." (PMID 35681772, 2022). "The methylation of GBP2 promoter was found in TNBC and associated with the malignant evolution of breast cancer." (PMID 33809079, 2021). "Future studies will determine the molecular mechanisms by which mGBP-2/GBP-2 regulate Rho GTPases to inhibit migration/invasion and contribute to improved prognosis in breast cancer." (PMID 34830789, 2021). "Previous reports have shown that GBP1 upregulation predicts a poorer prognosis in different types of cancer, including TNBC, whereas a higher level of GBP2 correlates with a favorable outcome in breast cancer." (PMID 33916322, 2021). "In this study, we examined the role of the murine ortholog of GBP-2 (mGBP-2) in the 4T1 model of murine breast cancer." (PMID 34830789, 2021). "Analysis of the correlation of GBP-2 expression and OS in 1879 patients also showed that high GBP-2 expression correlated with improved OS for a group including all breast cancers (Hazard ratio = 0.0.74 and 95% CI of 0.61–0.89)." (PMID 34830789, 2021). "On the other hand, GBP2 appeared to correlate with favorable prognosis in breast cancer and indicate an efficient T cell response." (PMID 33809079, 2021). "GBP2 appeared to correlate with better prognosis in breast cancer and indicate an efficient T cell response." (PMID 33916322, 2021). "Together these data demonstrate that GBP-2 is responsible for cell autonomous activities that make breast cancer cells less aggressive." (PMID 34830789, 2021). "New findings indicate that GBP2 regulates mitochondrial fission andsuppresses breast cancer invasion by blocking dynamin-related protein 1 (Drp1)translocation from the cytosol to mitochondria." (PMID 33211060, 2020). "For instance, GBP2 was found to inhibit mitochondrial fission and cell metastasis in breast cancer cells both in vitro and in vivo." (PMID 32765489, 2020). "GBP2 promotermethylation on both cfDNA and tumor tissues were positively correlated and wasdetected in about 88% of breast cancer patients mostly in (Lymph node positive)LN+ and higher stages." (PMID 33211060, 2020). "A region of GBP2 promoter methylation status in plasma andbreast tissues of breast cancer patients compared with normal control werestudied." (PMID 33211060, 2020). "The GBP2 promoter methylation in circulating DNAmay be considered as a possible effective non-invasive molecular marker in poorprognostic breast cancer patients with the evidence of its relation to disease stageand lymph node metastasis." (PMID 33211060, 2020). "Taken together, our data suggest that GBP2 specifically reduces invasion and is involved in regulating mitochondrial dynamics in metastatic breast cancer cells." (PMID 29072687, 2017). "We next tested increased GBP2 levels to determine the function in breast cancer cells with low GBP2 expression and found that exogenous GBP2 transfection led to a greater inhibition of metastasis in cells than did IFN-γ treatment." (PMID 29072687, 2017). "In conclusion, out data show for the first time that GBP2 directly interacts with Drp1, and we identify GBP2 as an inhibitory factor in breast cancer metastasis." (PMID 29072687, 2017). "Collectively, our data demonstrate that Drp1 and GBP2 have a physical interaction in breast cancer cells." (PMID 29072687, 2017). "In the present study, we found that GBP2 interacts with Drp1 and blocks translocation of Drp1 to mitochondria, thereby attenuating Drp1-dependent mitochondrial fission and invasion of breast cancer cells." (PMID 29072687, 2017). "In our study, we demonstrated that upregulation of GBP2 expression suppresses metastasis in breast cancer cells by inhibiting Drp-1-dependent mitochondrial fission, providing further understanding of the role and mechanism of GBP2 in breast cancer." (PMID 29072687, 2017).
breast carcinoma (continued). "Additionally, GBP2 expression is modulated by endocrine agents: it was significantly upregulated by estradiol and downregulated by tamoxifen in breast cancer models, implicating a role in hormone-therapy response." (PMID 41181145, 2025). "Due to its strong prognostic value, GBP2 has been incorporated into multi-gene prognostic models for several cancers, including bladder urothelial carcinoma, breast cancer, pancreatic carcinoma, ovarian cancer, primary central nervous system lymphoma, and cutaneous melanoma." (PMID 41181145, 2025). "GBP2 promotes breast cancer autophagy via ATG2, inhibiting PI3K/AKT/mTOR signaling and boosting immune sensitivity; while in osteosarcoma, it encourages immune cell infiltration (e.g., CD8+ T cells) to curb growth, driven by its homodimerization and cytokine regulation." (PMID 40564939, 2025). "Also, in the cohorts of GSE126044 (non-small cell lung cancer), GSE176307 (urothelial carcinoma), PRJEB23709 (melanoma), and MEDI4736 (breast cancer), GBP2 was substantially expressed in tumors with good immunotherapeutic response." (PMID 37784054, 2023). "Three of the members of this family are associated with breast cancer: GBP-1, GBP-2, and GBP-5." (PMID 35681772, 2022). "GBP-2 is down-regulated by promoter methylation in about 73.2% of breast cancers." (PMID 35681772, 2022). "GBP2 is an IFNγ-induced GTPase involved in protective immunity against microorganisms and is also a marker for an efficient T cell response in breast carcinomas." (PMID 36055241, 2022). "Also consistent is the role of GBP-2 in inhibiting mitochondrial fission, which inhibits breast cancer cell migration/invasion." (PMID 35681772, 2022). "GBP-2 correlated with improved RFS in the cohort containing all breast cancers and in ER− and TNBC." (PMID 35681772, 2022). "Clearly, more research on how GBP-2 promotes a better prognosis in breast cancer is needed." (PMID 35681772, 2022). "Guanylate-Binding Protein-2 has been correlated with better prognosis in breast cancer." (PMID 34830789, 2021). "GBP2 was found as a TGF-b target gene induced in metastatic breast cancer cells." (PMID 33688507, 2021). "In this study, we asked if the expression of GBP-2 in breast cancer merely provided a biomarker for improved prognosis or whether it actually contributed to improving outcome." (PMID 34830789, 2021). "This confirms that GBP-2 inhibits breast cancer cell migration." (PMID 34830789, 2021). "GBP2 promoter methylation was found in TNBC and associated with advanced stages of breast cancer." (PMID 33916322, 2021). "GBP-2 inhibits breast cancer cell invasion, in part, by inhibiting mitochondrial fission." (PMID 34830789, 2021). "Since GBP-2 expression correlates with improved prognosis in breast cancers, this study specifically addressed whether GBP-2 contributes to cell autonomous changes that could result in improved prognosis." (PMID 34830789, 2021). "Our data suggest that upregulation of GBP2 expression, a key step to block Drp1-dependent mitochondrial fission, may represent a novel strategy to prevent metastasis in breast cancers." (PMID 29072687, 2017). "Together, these results suggest that GBP2 interacts with endogenous Drp1 in breast cancer cells." (PMID 29072687, 2017). "Given that breast cancer cell metastasis can be regulated by mitochondrial dynamics, we tested whether GBP2 could alter mitochondrial networks." (PMID 29072687, 2017). "Furthermore, GBP2 blocks Drp1 translocation from the cytosol to mitochondria, thereby attenuating Drp1-dependent mitochondrial fission and breast cancer cell invasion." (PMID 29072687, 2017). "Moreover, animal experiments revealed that most control mice with mammary tumors developed massive lung metastases, but GBP2-expressing mice had significantly fewer lung metastases." (PMID 29072687, 2017).
breast carcinoma (continued). "Moreover, up-regulation of GBP2 expression corresponds to a better prognosis of breast cancer patients, and might participate in T-cell defense against breast cancer." (PMID 36341357, 2022). "This might be due to the fact that GBP2 could prevent dynamin-related protein 1 (Drp1) translocating from the cytoplasm to the mitochondria, thus weakening the Drp1-dependent mitochondrial fission and the invasion of breast cancer cells." (PMID 35356208, 2022). "Thus GBP2 may represent a new therapeutic target to suppress breast cancer metastasis through attenuation of Drp1-dependent mitochondrial fission." (PMID 29072687, 2017). "Importantly, GBP2 could predict the immunotherapeutic responses in at least four different cancer types, including melanoma, urothelial carcinoma, non-small cell lung cancer, and breast cancer." (PMID 37784054, 2023). "Expression difference analysis showed that GBP2, GPR171, DIRAS3, and RAC2 were significantly down-regulated in expression in metastatic breast cancer compared with primary breast cancer tumors." (PMID 36212434, 2022). "To clarify what we do and do not know about GBPs in breast cancer, the current literature on GBP-1, GBP-2, and GBP-5 in breast cancer has been assembled." (PMID 35681772, 2022). "GBP-2 also inhibits the TNF-α induction of matrix metalloproteinase-9 (MMP-9), known to play a role in breast cancer invasion." (PMID 35681772, 2022). "We performed expression analyses of five genes (GBP2, GPR171, DIRAS3, RAC2, CACNA1D) obtained from the LASSO model to observe their expressions in primary breast cancer and metastatic breast cancer." (PMID 36212434, 2022). "The analysis showed that only GBP2, GPR171, DIRAS3, and RAC2 were significantly down-regulated in expression in metastatic breast cancer compared with primary breast cancer tumors." (PMID 36212434, 2022). "Furthermore, macrophages with elevated Gbp2 expression significantly inhibit tumor growth in both ID8 ovarian cancer and 4T1 breast cancer models." (PMID 39985265, 2025). "The analysis showed that GBP2 was not significantly different from the overall survival of breast cancer patients, while GPR171, DIRAS3, and RAC2 were strongly associated with the overall survival of breast cancer patients." (PMID 36212434, 2022). "Unlike GBP-1 and GBP-5, all the literature on GBP-2 and breast cancer indicates that it is protective." (PMID 35681772, 2022). "Thus targeting GBP2, an IFN-γ inducible protein, represents a novel approach for suppressing breast cancer invasion." (PMID 29072687, 2017). "GBP-2 is not a bystander protein that just correlates with improved prognosis in breast cancers." (PMID 34830789, 2021). "As many proteins respond to IFN-γ stimulation, we needed to determine whether the effects of IFN-γ on invasion and mitochondrial dynamics in breast cancer cells were dependent on induction of GBP2, rather than other inducible proteins." (PMID 29072687, 2017).